GATA6 (GATA binding protein 6)
Description:
Transcriptional activator. Regulates SEMA3C and PLXNA2. Involved in gene regulation specifically in the gastric epithelium. May regulate genes that protect epithelial cells from bacterial infection. Involved in bone morphogenetic protein (BMP)-mediated cardiac-specific gene expression (By similarity). Binds to BMP response element (BMPRE) DNA sequences within cardiac activating regions (By similarity). In human skin, controls several physiological processes contributing to homeostasis of the upper pilosebaceous unit. Triggers ductal and sebaceous differentiation as well as limits cell proliferation and lipid production to prevent hyperseborrhoea. Mediates the effects of retinoic acid on sebocyte proliferation, differentiation and lipid production. Also contributes to immune regulation of sebocytes and antimicrobial responses by modulating the expression of anti-inflammatory genes such as IL10 and pro-inflammatory genes such as IL6, TLR2, TLR4, and IFNG. Activates TGFB1 signaling which controls the interfollicular epidermis fate.
Tractability: PROTAC: UniProt records ubiquitination sites on it.
Gene: Protein-coding gene on chromosome 18 (22,168,837 to 22,204,154, forward strand). Ensembl gene ENSG00000141448.
Subcellular location: Nucleus
Subcellular location (Human Protein Atlas): Nucleoplasm
Pathways (Reactome):
Developmental Biology: Cardiogenesis; Developmental Lineage of Multipotent Pancreatic Progenitor Cells; Formation of definitive endoderm; POU5F1 (OCT4), SOX2, NANOG repress genes related to differentiation
Hemostasis: Factors involved in megakaryocyte development and platelet production
Metabolism of proteins: Surfactant metabolism
Gene Ontology:
Molecular function: DNA-binding transcription factor activity; DNA-binding transcription factor activity, RNA polymerase II-specific; DNA-binding transcription factor binding; NFAT protein binding; protein binding; protein kinase binding; sequence-specific double-stranded DNA binding; transcription cis-regulatory region binding; transcription coactivator binding; RNA polymerase II cis-regulatory region sequence-specific DNA binding; chromatin binding; DNA binding; RNA polymerase II-specific DNA-binding transcription factor binding; sequence-specific DNA binding; zinc ion binding
Biological process: cardiac vascular smooth muscle cell differentiation; cellular response to hypoxia; G1 to G0 transition involved in cell differentiation; intestinal epithelial cell differentiation; male gonad development; negative regulation of apoptotic process; negative regulation of DNA-templated transcription; negative regulation of sebum secreting cell proliferation; negative regulation of transcription by RNA polymerase II; negative regulation of transforming growth factor beta1 production; negative regulation of transforming growth factor beta2 production; outflow tract septum morphogenesis; positive regulation of angiogenesis; positive regulation of cardiac muscle myoblast proliferation; positive regulation of DNA-templated transcription; positive regulation of transcription by RNA polymerase II; regulation of antimicrobial humoral response; response to growth factor; response to retinoic acid; response to xenobiotic stimulus; sebaceous gland cell differentiation; skin epidermis development; smooth muscle cell differentiation; atrioventricular canal development; atrioventricular node development; and 11 more
Cellular component: nucleoplasm; nucleus; chromatin; transcription regulator complex
Genetic constraint (gnomAD): Loss-of-function variants: 11 observed, 34.55 expected, observed/expected ratio (o/e) 0.32, 90% interval 0.2 to 0.53. The synonymous counts are far from expectation, so gnomAD's model fits this gene poorly and the ratio says little. Missense variants: 735 observed, 658.29 expected, observed/expected ratio (o/e) 1.12, 90% interval 1.05 to 1.19. Synonymous variants: 388 observed, 304.11 expected, observed/expected ratio (o/e) 1.28, 90% interval 1.17 to 1.39.
Gene-disease validity (ClinGen):
ClinGen rates the evidence that GATA6 causes each of these diseases.
GATA6-related congenital heart disease with or without pancreatic agenesis or neonatal diabetes (autosomal dominant): Definitive. A congenital heart disease that is present at birth.
dilated cardiomyopathy (autosomal dominant): Limited. Cardiomyopathy which is characterized by dilation and contractile dysfunction of the left and right ventricles.
Homologues: Orthologues: chimpanzee GATA6 (99% identical), macaque GATA6 (99% identical), dog GATA6 (94% identical), pig GATA6 (93% identical), rat Gata6 (90% identical), mouse Gata6 (89% identical), guinea pig GATA6 (54% identical), tropical clawed frog gata6 (50% identical), zebrafish gata6 (46% identical), Drosophila melanogaster srp (22% identical), Drosophila melanogaster GATAd (20% identical), Caenorhabditis elegans elt-2 (12% identical), and 1 more. Paralogues in human: GATA4 (36% identical), GATA5 (31% identical), GATA3 (26% identical), GATA2 (26% identical), GATA1 (22% identical), TRPS1 (16% identical), ZGLP1 (6% identical).
Diseases named in the same sentence as GATA6 in open-access papers:
GATA6 is named in the same sentence as 228 diseases in open-access papers, as found by Europe PMC text mining. Sharing a sentence is not in itself a finding about the gene and the disease. The quoted sentences say what the papers report.
pancreatic cancer (51 papers, 2008 to 2025). "In another study, both GATA3 and GATA6 were found to be upregulated in pancreatic cancer, with GATA3 expression closely associated with immune cell infiltration signatures, highlighting its potential role in modulating the tumor microenvironment." (PMID 41514651, 2025). "Our study identifies how oncogenic KRAS/ERK signaling suppresses GATA6 to cause dedifferentiation in pancreatic cancer." (PMID 41329526, 2025). "This study suggested that GATA6 defines an immune-enriched phenotype, which is associated with favorable outcomes for pancreatic cancer patients undergoing preoperative treatment." (PMID 40264765, 2025). "High GATA6 levels contribute to the classical pancreatic cancer subtype, which is associated with a higher degree of tumor differentiation and better disease prognosis." (PMID 41329526, 2025). "These further validate the loss of GATA6 signaling and Wnt/β-catenin signaling during the progression of human pancreatic cancers." (PMID 35536676, 2022). "Taken together, these results indicate that downregulation of GATA6 mediated the PORCN inhibitor resistance caused by p300 loss in RNF43-mutant pancreatic cancers." (PMID 35536676, 2022). "Conversely, in pancreatic cancer models driven by Kras mutations, GATA6 inhibits tumor progression by regulating epithelial differentiation." (PMID 32157212, 2020). "We also noted increased GATA6 expression in pancreatitis, which is a known risk factor for developing pancreatic cancer, and suggests a possible mechanistic link." (PMID 18535672, 2008). "Our discovery of GATA6 amplification provides a new foothold into understanding the pathogenic mechanisms underlying pancreatic cancer, and suggests new strategies for therapy by targeting GATA6 or the genes it regulates." (PMID 18535672, 2008). "We determined whether p300 loss and hence GATA6 suppression led to dedifferentiation in pancreatic cancer." (PMID 35536676, 2022). "Loss of p300/GATA6 axis changes pancreatic cancer subtype and bypasses Wnt dependency." (PMID 35536676, 2022). "GATA6 is a known lineage specification factor amplified in adenocarcinomas of the upper gastrointestinal tract, promoting adenocarcinoma but not squamous cell carcinoma survival in the esophagus, and whose loss induces a shift in pancreatic cancer from adenocarcinoma to squamous metabolic phenotype." (PMID 34656143, 2021). "Here, we report that oncogenic KRAS-activated ERK signaling suppresses GATA6 transcription in pancreatic cancers." (PMID 41329526, 2025). "While GATA6’s involvement in pancreatic cancer and EMT regulation via Slug in breast cancer is established, its functions in CAFs remain underexplored." (PMID 40216762, 2025). "This comprehensive review has offered enlightening insights into the indispensable roles GATA6 assumes in pancreas development, physiological processes, inflammation, and the intricate landscape of pancreatic cancer pathology." (PMID 39717718, 2025). "Another study used GATA6 expression as a biomarker to distinguish basal-like from classical pancreatic cancer subtypes." (PMID 41514651, 2025). "Targeting the TET3/GATA6 axis in combination with ferroptosis and epigenetic modulators offers a promising strategy to overcome therapeutic resistance in aggressive pancreatic cancer." (PMID 40567112, 2025). "In this context, GATA6 was identified and comprehensively characterized as a newfound candidate lineage-specific oncogene, undergoing amplification specifically within pancreatic cancer." (PMID 39717718, 2025). "The expression of GATA4 and GATA6 are linked to the differentiation level and grading of pancreatic cancer, whereas lower GATA4 and higher GATA6 levels are connected to survival rates." (PMID 40699746, 2025). "GATA6 is a master regulator of differentiation in the pancreas, and its expression levels determine the 2 main molecular subtypes of pancreatic cancer." (PMID 41329526, 2025).
pancreatic cancer (continued). "The outcomes of this investigation highlight that the amplification of GATA6 (i.e., the presence of additional gene copies) and its abnormal overexpression significantly contribute to the initiation of pancreatic cancer." (PMID 39717718, 2025). "For instance, GATA6 was shown to distinguish classical from basal-like molecular subtypes in pancreatic cancer." (PMID 41514651, 2025). "As GATA6 expression is known to correlate with Wnt signaling dependency in pancreatic cancer cells, reduced GATA6 expression suggests a Wnt-independent nature of Ep_VGLL1." (PMID 38297291, 2024). "In animal models, nicotine promotes pancreatic cancer by inducing dedifferentiation of acinus cells by downregulating GATA6." (PMID 36674311, 2023). "Last but not least, our findings provide a rationale for using p300 and GATA6 expression status to further stratify patient selection in RNF43-mutant pancreatic cancers to maximize the clinical efficacy of Wnt inhibitors." (PMID 35536676, 2022). "This identifies a more general role for a p300/GATA6 axis in cancer and suggests that p300 and GATA6 status can be used to stratify RNF43-mutant pancreatic cancer patients to maximize the clinical benefits of PORCN inhibitors." (PMID 35536676, 2022). "Taken together, these results indicate that loss of p300 induced a phenotypic transition (dedifferentiation) of pancreatic cancer, mediated at least in part by the downregulation of GATA6." (PMID 35536676, 2022). "The roles of GATA6 in regulating differentiation in normal pancreas and pancreatic cancer are well established." (PMID 35536676, 2022). "Consistent with this, the Sato and Clevers labs reported that the GATA6-high classical subtype tumor cells from RNF43-WT pancreatic cancers rely on Wnts to grow as organoids ex vivo." (PMID 35536676, 2022). "GATA6 expression levels also positively correlate with the dependency on exogenous Wnts in the ex vivo culture of pancreatic tumor organoids." (PMID 35536676, 2022). "Of note, a previous study found that in ex vivo culture of pancreatic tumor organoids, downregulation of GATA6 promoted the expression of cancer cell–derived Wnt ligands, e.g., WNT7B, making some of these organoids “exogenous Wnt”-independent." (PMID 35536676, 2022). "Real and colleagues recently reported an elegant work showing the tumor-suppressive function of GATA6 in pancreatic cancer." (PMID 32596145, 2020). "GATA6 has been suggested to be oncogenic in multiple cancers and pre-cancerous lesions, including Barrett’s esophagus, gastric cancer, pancreatic cancer, and colon cancer." (PMID 24472151, 2014). "GATA6 plays a significant role in human pancreatic organogenesis, and is amplified and overexpressed in pancreatic cancer." (PMID 24454681, 2014). "GATA6 has been shown to be frequently overexpressed in pancreatic cancer, but is amplified in only a minority of cases." (PMID 23861445, 2013). "GATA6 is an oncogene that is involved in pancreatic cancer invasion and is overexpressed in nearly all pancreatic tumors." (PMID 23861445, 2013). "Previous study also demonstrated that the Gata6 gene regulated Wnt signaling pathway which played a core role in epithelial stem cell development and airway regeneration, and in pancreatic cancer GATA6 activates Wnt signaling." (PMID 22952821, 2012). "In pancreatic cancer tissues, GATA6 overexpression was significantly correlated with nuclear accumulation of ß-catenin protein (8/12 PDACs with GATA6 overexpression showing ß-catenin nuclear accumulation versus 3/20 without GATA6 overexpression, p = 0.004)." (PMID 21811562, 2011). "Although GATA6 amplification has been reported in pancreatic cancer cell lines and xenografts, when GATA6 amplification occurs during the step-wise progression of pancreatic intraepithelial neoplasia has not." (PMID 21811562, 2011). "Forced overexpression of DKK1 antagonized the effects of GATA6 on Wnt signaling in pancreatic cancer cells." (PMID 21811562, 2011).
pancreatic cancer (continued). "We report here the discovery of amplification (i.e. extra copies) of the GATA6 gene in many human pancreatic cancers." (PMID 18535672, 2008). "When amplified, GATA6 was overexpressed at both the mRNA and protein levels, and strong immunostaining was observed in 25 of 54 (46%) primary pancreatic cancers compared to 0 of 33 normal pancreas specimens surveyed." (PMID 18535672, 2008). "To assess the frequency with which GATA6 exhibited elevated expression in primary pancreatic cancer, we performed IHC on a tissue microarray (TMA) that included cases of normal pancreas, pancreatitis and pancreatic ductal adenocarcinoma." (PMID 18535672, 2008). "We observed moderate and strong GATA6 nuclear staining respectively in 15 (28%) and 25 (46%) of 54 primary pancreatic cancers compared to just 3 (9%) and 0 (0%) of 33 normal pancreas specimens surveyed (P<0.001, χ2 test)." (PMID 18535672, 2008). "siRNA mediated knockdown of GATA6 in pancreatic cancer cell lines with amplification led to reduced cell proliferation, cell cycle progression, and colony formation." (PMID 18535672, 2008). "While GATA6 was amplified in 19% of xenograft specimens, it was highly expressed at the protein level in 46% of primary pancreatic tumors surveyed." (PMID 18535672, 2008). "However, the tumor tissue expression of GATA6 has been suggested to identify prognostic signatures in treatment-naive patients with pancreatic cancer, making it a prime candidate for further investigation in T cells." (PMID 40989699, 2025). "However, why GATA6 expression varies across pancreatic cancers and what regulates GATA6 expression remain elusive." (PMID 41329526, 2025). "Increased levels of GATA6 expression enhance pancreatic cancer cell growth." (PMID 39717718, 2025). "GATA6 mRNA levels inversely correlated with KRAS/ERK activity in pancreatic tumors." (PMID 41329526, 2025). "Notably, GATA6 protein abundance was also markedly reduced in the RNF43/EP300-mutant pancreatic cancer cell lines, and reexpressing p300 in EP300-mutant PL45 cells upregulated GATA6 expression." (PMID 35536676, 2022). "Supporting a functional role as an enhancer, the sequence of this intronic region is highly conserved in vertebrates, and its H3K27Ac signal correlates well with the GATA6 expression levels in both diverse human pancreatic cancer cells and mouse intestine during development." (PMID 35536676, 2022). "While there has been a substantial role identified for GATA6 in pancreatic cancer by using organoid models of this disease, there have been a paucity of studies examining mechanisms of GATA6 action during islet development or function using either hPSC- or primary organ-derived organoids." (PMID 36339450, 2022). "Based on our observation that Wnt inhibition drives an increase in cancer cell–derived Wnt production, we propose instead that the elevated expression of several Wnts in the GATA6-low pancreatic tumors is due to a compensatory feedback response, reacting to the loss of Wnt/β-catenin signaling." (PMID 35536676, 2022). "The GATA6 genomic locus is hypermethylated in the GATA6-low basal-like pancreatic tumors, although this may be a late event that reinforces rather than establishes GATA6 silencing." (PMID 35536676, 2022). "In addition, 5hmC is concentrated in the promoter region of the oncogene GATA6 in pancreatic cancer." (PMID 32774324, 2020). "The chromatin modifier KDM6A, which has been implicated in the progression of squamous PDAC, is a common mutation shared by GSK3b inhibitor-sensitive PDCLs, and in keeping with reported findings, we observe squamous-like pancreatic cancer in these PDCLs despite the presence of GATA6." (PMID 32402285, 2020). "Similarly, in PDAC, GATA6 was amplified in a subset of pancreatic tumors, and overexpression of GATA6 increased pancreatic cancer proliferation." (PMID 30674866, 2019).